SOX10 (SRY-box transcription factor 10)
Diseases named in the same sentence as SOX10 in open-access papers (continued):
Sharing a sentence is not in itself a finding about the gene and the disease.
metastatic melanoma (31 papers, 2012 to 2026). A melanoma that has spread from its primary site to another anatomic site. "Here we report a challenging case of a 59-year-old male with splenic metastatic melanoma which revealed a loss of four diagnostic melanocytic markers including S100, SOX-10, HMB45, and MART-1, but a gain of SOX-11." (PMID 39258061, 2024). "Immunohistochemistry was positive for S100, Melan-A, and SOX10, with a high Ki67 proliferation index of 90%, confirming the diagnosis of metastatic malignant melanoma." (PMID 41142597, 2025). "SOX10 is a protein homogeneously expressed in primary and metastatic melanoma and is essential for melanocyte differentiation." (PMID 41012776, 2025). "Histopathological examination confirmed metastatic melanoma, positive for SOX10, HMB45, and Ki67 markers." (PMID 40182333, 2025). "In addition, SOX10 could be a diagnostic marker for metastatic melanoma in sentinel lymph nodes." (PMID 40342816, 2025). "The results revealed that SOX10 immunostaining successfully identified metastatic melanoma in all examined cases, achieving a 100% detection rate." (PMID 39611156, 2024). "Other highly malignant tumors such as metastatic melanoma (SOX-10 marker) and lymphoma (CD-19, PAX-5, terminal deoxynucleotidyl transferase (TdT) markers, etc.)should also be considered in differentials." (PMID 37113364, 2023). "H&E stains of primary and metastatic melanoma (N = 77) were digitized, re-stained with SOX10, and re-scanned." (PMID 36361209, 2022). "Melan-A and SOX10, a marker used to identify metastatic melanoma, were assessed by qPCR, demonstrating significantly higher values for hPL cultured cells compared to FBS supplemented cells." (PMID 34768746, 2021). "For all patients, IHC staining of S100, MelanA, and SOX10 confirmed these cell lines to be metastatic melanoma." (PMID 34187852, 2021). "Histopathology from T10 vertebral body was suggestive of metastatic melanoma and immunohistochemistry showed strongly positive SOX10, MITF, HMB45, and S100 confirmed metastatic melanoma." (PMID 26989537, 2016). "In contrast, SOX10 has emerged as a reliable marker for detecting metastatic melanoma." (PMID 40598734, 2025). "We detected overlapping expressions of cytoplasmic DEPDC1B and SOX10 transcription factor in a large percentage of nevus, primary, and metastatic melanomas (86/98; 87.8%) compared with specimens expressing DEPDC1B alone (11/98; 11.2%) or expressing neither protein (1/98; 1%)." (PMID 35088579, 2022). "Other studies have also demonstrated that the percentage level of SOX10-positive tumor cells may vary considerably in both primary and metastatic melanoma." (PMID 36361209, 2022). "In addition, due to high sensitivity and specificity, SOX10 can also serve as a diagnostic marker for sentinel lymph node metastatic melanoma." (PMID 40342816, 2025). "The SOX10 promoter has previously been shown to be epigenetically silenced in human gastric cancers and metastatic melanoma, the basal level of Sox10 expression is low in vitro, we hypothesized that Sox10 gene induction could be due to gene demethylation in SLK-/- NDL cells." (PMID 33985544, 2021). "Finally, the analysis of an online database of metastatic melanoma patient-derived tissues (GEO accession number: GDS3966) confirmed similar inversed tendency between SOX10 and ID3 expression on one hand and between MITF and ID3 expression on the other hand (46 samples and 48 samples respectively)." (PMID 29299138, 2017). "Tru-cut biopsy revealed a malignant neoplasm positive for SOX10 and HMB45, with immunohistochemistry insufficient to differentiate CCS from metastatic melanoma." (PMID 42077576, 2026). "On the other hand, the expression of SOX10 and S100 makes the possibility of an MPNST and a metastatic melanoma important considerations." (PMID 39196362, 2024).
metastatic melanoma (continued). "As expected, CDC16 was ubiquitously expressed in all the analyzed specimens, but we detected a positive correlation between SOX10 and SCUBE3 expressions in metastatic melanomas (n = 19/22)." (PMID 35088579, 2022). "To address this issue, we first performed comparative expression study of these factors on tissue sections from Chinese patients with benign melanocytic nevus, primary dermal and metastatic melanomas using antibodies specific for SOX9, SOX10, and NEDD9." (PMID 30642390, 2019). "The SOX10‐regulated DEPDC1B expression to stabilize SCUBE3 for promoting angiogenesis and metastasis was further supported by their high correlation of expression with microvessel density in metastatic melanoma specimens." (PMID 35088579, 2022). "Although our study mostly detected SOX10-negative cells in metastatic melanoma, presence of negative tumor cells is an unavoidable limitation of the proposed SOX10 annotation technique." (PMID 36361209, 2022). "Further tumor immunohistochemistry revealed extensive neuroendocrine differentiation with CD56, synaptophysin, and INSM1, as well as strong immunoreactivity for melanocyte markers including SOX10, S100, PRAME, and MITF, consistent with metastatic melanoma with neuroendocrine differentiation." (PMID 34926265, 2021).
deafness (27 papers, 2010 to 2024). An inherited or acquired condition characterized by the complete loss of the ability to hear from one or both ears. "Mutations in SOX10 result in abnormal pigment distribution and deafness, and are the primary cause of WS." (PMID 34426786, 2021). "Loss-of-function mutations in another transcription factor of the SOX family, SOX10, were linked to KS associated with deafness." (PMID 34198905, 2021). "Targeted sequencing of 415 deafness-related genes identified the heterozygous c.481C>T (p.R161C) mutation in SOX10 and the homozygous c.235delC (p.L79Cfs∗3) mutation in GJB2 as separate pathogenic mutations in distinct affected family members." (PMID 32908489, 2020). "Pathogenic variants of SOX10 account for 30% of cases of KS (hypogonadotropic hypogonadism and anosmia due to olfactory bulb agenesis) with deafness." (PMID 33362852, 2020). "Mutations of PAX3 and SOX10 are responsible for deafness in several forms of human Waardenburg syndrome." (PMID 26664958, 2015). "Therefore, SOX10 mutation analysis should be considered for KS patients with combined WS clinical manifestations, especially deafness." (PMID 33597923, 2020). "It is speculated that SOX10 mutation may lead to KS because KS patients with deafness have similar clinical manifestations to WS patients with anosmia." (PMID 33597923, 2020). "Recently, mutations in the well-known WS pathogenic gene SOX10 have been found in some KS patients with deafness, but whether SOX10 is a co-pathogenic gene of KS and WS remains uncertain." (PMID 33597923, 2020). "While our manuscript was in revision, another study was published showing that loss-of-function mutations in SOX10 cause Kallmann's syndrome with deafness and describing the same OEC phenotype in Sox10 mutant mice, thus implicating neural crest-derived OECs in the aetiology of Kallmann's syndrome." (PMID 23862023, 2013). "It has the function of maintaining the survival and differentiation of cochlear precursor cells, suggesting that there may be other pathways regulating the development of the inner ear in addition to the MITF pathway and in the mechanism of deafness caused by SOX10 mutation." (PMID 33597923, 2020). "Four recessive (TRIOBP, SLC26A4, GJB2, COL4A3) and one dominant (SOX10) for the deafness; six recessive genes (LRGUK, DNAH9, ARMC4, DNAH2, RSPH6A, and ACE) for male infertility can be conclusively ascribed." (PMID 38884051, 2024). "Our results showed that mutations in SOX10 and MITF are two major causes of deafness associated with WS, and de novo mutations were frequently found in probands with SOX10 mutations but not in those with MITF mutations." (PMID 31960627, 2020). "Recently, mutations in SOX10 have been identified in a few patients with Kallmann syndrome (KS, OMIM 308700) with deafness, which is characterized by hypogonadotropic hypogonadism, anosmia and hearing loss." (PMID 32908489, 2020). "Our results showed that mutations in SOX10 and MITF are two major causes for deafness associated with WS, and de novo mutations were frequently found in probands with SOX10 mutations (3/4) but not in those with MITF mutations (0/2)." (PMID 31960627, 2020). "More importantly, these data demonstrate the possibility that some of these deafness genes affect multiple SV cell types, as in the case of Mitf and Sox10, which are expressed in both intermediate and marginal cells." (PMID 31920542, 2019). "Our results showed that mutations in SOX10 and MITF are two major causes for deafness associated with WS2." (PMID 27759048, 2016). "No significant loci were located within or near the genes MITF, SILV, SOX10, or KITLG, shown in other studies to be associated with deafness." (PMID 26664958, 2015). "The gene Sox10, a candidate gene involved in pigmentation and in deafness in other species and present on CFA10, was sequenced in unilateral, bilateral deaf and hearing dogs." (PMID 20967282, 2010).
deafness (continued). "They found that numerous deafness-related genes (e.g. Col9a2, Lmx1a, and Sox10) were downregulated, and single-cell transcriptome data from Chd7KO/+ organoids also showed that some deafness-related genes (e.g. Six1, Ush1c, and Strc) were downregulated in HCs, implying that." (PMID 38015350, 2024). "It is well known that SOX10 is an important pathogenic gene associated with WS2 and WS4, and KS with deafness is similar to WS with anosmia in many clinical manifestations, such as perceptive nervous deafness, abnormal pigmentation, and hyposmia." (PMID 33597923, 2020). "SOX10 is a key transcription factor in the migration and differentiation of NCC, and its mutations lead to abnormal differentiation of NCC-derived melanocytes, which results in abnormal pigment distribution and deafness and is the main cause of WS." (PMID 32908492, 2020). "A candidate pigmentation and deafness gene located within the locus was Sox10; however, sequencing of the gene in six hearing, two unilaterally deaf, and two bilaterally deaf dogs did not demonstrate any deafness-associated Sox10 mutations." (PMID 26664958, 2015). "Loss of Sox10 results in absence of most NC derivatives, whereas Sox10 haploinsufficiency causes Waardenburg Hirschsprung syndrome, characterized by aganglionic megacolon, pigmentary abnormalities and often deafness due to loss of sensory innervation." (PMID 25629959, 2015). "Eighteen SNPs were identified in gDNA in exon and flanking sequences of Sox10 in Australian Stumpy-tail Cattle dogs, however none were clearly associated with the deafness phenotype." (PMID 20967282, 2010). "Again, the chromosomal region 1 Mb up- and downstream of SOX10 (CFA10:25680441-27690530) was checked using IGV, but no deafness associated variants including larger structural variants were identified." (PMID 33805165, 2021). "Phenotypes caused by the genes endothelin 3 (END3), endothelin receptor B (EDNRB), microphthalmia-associated transcription factor (MITF), paired box 3(PAX3), SRY-box 10 (SOX10), and snail homolog 2 (SNAI2) can result in decreased melanocytes, white coat color, and ultimately deafness." (PMID 27698666, 2016). "The closest recognized gene associated with deafness was SOX10, which is mutated in human Waardenburg Syndrome type IVc and plays a role in regulating MITF, but sequencing in six hearing, two unilaterally deaf, and two bilaterally deaf dogs did not reveal any disease-associated mutations in SOX10." (PMID 32413090, 2020). "Thus, a Sox10 mutation in ASCD could change coat colour, possibly cause white speckling and deafness through a lack of melanocyte function in the inner ear and altered neural crest development." (PMID 20967282, 2010).
Waardenburg-Shah syndrome (26 papers, 2008 to 2025). Waardenburg-Shah syndrome (WSS) is a neurocristopathy characterized by the association of Waardenburg syndrome (sensorineural hearing loss and pigmentary abnormalities) and Hirschsprung disease. "Type IV or Waardenburg-Shah syndrome is associated with mutations in either Sry BOXIO transcription factor (SOX10), at 22q13.1, Endothelin 3 (EDN3), at 20q13, or Endothelin Receptor Type B (EDNRB) on chromosome 13q22.321,22." (PMID 30854529, 2017). "Sox10 mutations lead to several craniofacial abnormalities in humans, called neurocristopathies, including Waardenburg-Hirschsprung syndrome and peripheral neuropathies." (PMID 25309446, 2014). "Mutations in the genes encoding the EDN receptor B (EDNRB), its ligand EDN3, and the transcription factor SOX10 cause Waardenburg-Shah syndrome (also known as Waardenburg syndrome type IV), comprised of pigment cell abnormalities and Hirschsprung’s disease." (PMID 24040226, 2013). "Animal studies have indicated that SOX10 is one of the key transcription factors regulating the proliferation, migration and differentiation of multipotent neural crest (NC), and mutation of SOX10 in humans may lead to type 4 Waardenburg syndrome (WS)." (PMID 34453037, 2021). "These two enhancers and the genomic architecture around Sox10, as revealed by Hi-C data, shed light on the OL regulation of Sox10 expression and the pathology of Waardenburg-Shah syndrome that results from genomic deletions involving Sox10-E1 and Sox10-E2." (PMID 40644525, 2025). "In the Hry model of Waardenburg syndrome type IV, Sox10 expression is strongly downregulated owing to transgene-insertion-mediated deletion of a strong enhancer, a mechanism that has subsequently been reported to occur in humans as well." (PMID 27585883, 2016). "Hence, genomic deletions involving Sox10-E1 and Sox10-E2 would perturb not only SOX10, but also PICK1 and other genes, and may cause a pathology that is more complex than that of conventional Waardenburg-Shah syndrome that results from SOX10 coding mutations." (PMID 40644525, 2025). "Human loss-of-function SOX10 mutations result in Waardenburg-Shah Syndrome (WS4; OMIM Accession No. 277580), a disorder characterized by impaired pigmentation and aganglionic megacolon consistent with Hirschsprung's Disease." (PMID 18773071, 2008). "Scarcely, Waardenburg syndrome type IV might present with mild neuronal symptoms, especially when the SOX10 (SRY-related HMG-box gene 10) gene is involved." (PMID 31998473, 2020).
neurofibroma (25 papers, 2013 to 2025). An intraneural or extraneural neoplasm arising from nerve tissues and neural sheaths. "Immunohistochemically, the neurofibroma component is positive for S100, SOX10, EMA, Claudin-1, and GLUT-1, while the perineurioma component does not express S100." (PMID 40218204, 2025). "In contrast, neurofibromas displayed patchier S100/SOX10 staining and slightly higher Ki67 (3%), though still within benign thresholds." (PMID 41359213, 2025). "Immunohistochemically, schwannomatous areas are strongly positive for S100 and SOX10, whereas the neurofibroma component expresses S100, SOX10, CD34, EMA, and GLUT-1." (PMID 40218204, 2025). "Histopathology confirmed a diffuse-type cellular neurofibroma with patchy S100 and SOX10 positivity, focal CD34 expression, and low Ki-67, supporting a benign profile." (PMID 41446319, 2025). "These neurofibromas exhibited classic diffuse-type histologic morphology and expected patterns of S100, SOX10, GFAP, and CD34 immunohistochemistry." (PMID 37817770, 2023). "Immunohistochemically, neurofibroma is typically an S100-protein- and SOX10-positive tumor with a variable expression of CD34 and EMA." (PMID 35741273, 2022). "SOX10 expression is down-regulated in NF1−/− neurofibromas, and it is possible that RUNX1/3 binds to this TF-binding motif in our system to drive neurofibromagenesis." (PMID 31032403, 2019). "In patients with neurofibromas, S100 and SOX10 expression was observed in all cases." (PMID 41359213, 2025). "In contrast, one would expect variable Sox10 reactivity in neurofibroma." (PMID 35622732, 2022). "Although immunohistochemistry does not significantly aid in distinguishing ANNUBP from neurofibromas, varying degrees of loss in S-100/SOX-10 expression and the CD34+ fibroblast network may correlate with tumor malignancy." (PMID 40308487, 2025). "Although immunohistochemical analyses are not helpful for the diagnosis of ANNUBP, a variable to complete loss of S100 protein/SOX10 expression and a loss of the CD34-positive fibroblastic network, typically found in all types of neurofibromas, may be suggestive." (PMID 35741273, 2022). "Nuclear Sox-10 immunoreactivity, which was consistently visualized in healthy nerves, was present in many neoplastic cells with a diffuse or patchy distribution in all NST tumors including neurofibromas." (PMID 36669002, 2022). "Only one neurofibroma was negative for Sox10, but this was without an internal control to confirm the successful staining reaction." (PMID 35622732, 2022). "While immunohistochemical analysis has limited utility in diagnosing ANNUBP, a complete absence of S-100 protein/SOX-10 expression and the loss of the CD34+ fibroblast network, typically found in all neurofibroma variants, may serve as useful diagnostic indicators." (PMID 40308487, 2025). "Downregulation of differentiation markers such as SOX10 was found in the least aggressive subtype of MPNSTs relative to neurofibromas, and this has also been shown in a comparison of MPNSTs with normal Schwann cells, supporting appropriateness of the neurofibromas as a non-malignant reference." (PMID 37837931, 2023).
cutaneous melanoma (22 papers, 2015 to 2025). A primary melanoma arising from atypical melanocytes in the skin. "Overall, these data suggest that TAZ is the major co-activator of the TEAD transcriptome in SOX10-low cutaneous melanoma cells." (PMID 41193428, 2025). "Recently, an improved DL annotation method for H&E/SOX10 dual stains was developed to better identify tumor cells in cutaneous melanoma." (PMID 38241314, 2024). "Significant discoveries revealed increased regulon activities of SOX10, a protein that facilitates the transformation of cutaneous melanoma cells into a condition that is tolerant to targeted inhibitors." (PMID 39187937, 2024). "Here, the authors show the presence of a dormant-invasive SOX10- subpopulation in cutaneous melanoma that can be targeted by cIAP1/2 inhibitors." (PMID 35296667, 2022). "SOX-10 has been shown to be a sensitive marker of cutaneous melanoma, including desmoplastic subtype, which is known to be negative for melanocytic markers such as Melan A and HMB-45." (PMID 26316887, 2015). "Also, when comparing SOX10 expression in different types of malignancies in the TCGA database, we found that cutaneous melanoma highly expressed SOX10 compared to other cancers." (PMID 40956859, 2025). "SOX-10 has been shown to be a sensitive marker of cutaneous melanoma." (PMID 26316887, 2015). "In addition, SOX10 was recently identified as an oncogene in skin melanoma that could be inhibited by the miRNA miR-3138." (PMID 33046735, 2020). "All excised tumors were diagnosed as primary cutaneous melanomas with rhabdoid differentiation based on histomorphological findings and immunohistochemistry considering S100, MART-1, SOX-10, HMB-45, vimentin and desmin." (PMID 35645230, 2022). "Investigating 448 cutaneous melanomas from the TCGA PanCancer Atlas, we discovered a positive correlation between high ATP1A1 mRNA expression and markers of differentiation and pigmentation (MITF, SOX10, TYR, MLANA)." (PMID 38178183, 2024).